MED12 (mediator complex subunit 12)
Diseases named in the same sentence as MED12 in open-access papers (continued):
Sharing a sentence is not in itself a finding about the gene and the disease.
tumor (continued). "The positive correlation of MED12 mutations with LM tumor numbers in the uterus has been reported previously, and the reason for this may surround the increased oxidative stress found with high numbers of LM occur, shown in this study." (PMID 35869560, 2022). "Considering that all cases harboured the same pattern of MED12 mutations within each case, the secondary resected tumours seemed to be genetically identical to the primary tumours, suggesting that they were truly recurrent tumours." (PMID 33046803, 2021). "In addition to its role as a driver gene, MED12 alterations are associated with clinical features of uLM including tumor size, conventional histology, and subserosal location as well as diagnosis of multiple vs. single uLM." (PMID 34445194, 2021). "In karyotypically normal ULs, MED12 mutations were detected in four out of nine tumours." (PMID 34944592, 2021). "The present tumor was shown to lack mutations in the corresponding hotspot region of MED12." (PMID 33292379, 2020). "Deletion or mutation within MED12 oncogene may act as a tumor suppressor by inhibiting chemotherapy-induced apoptosis." (PMID 32766158, 2020). "However, in the organotypic culture we observed that both, point mutation and in-frame deletion alleles of MED12, preferentially expressed in original tumour, are maintained in derived cultures slices." (PMID 32251338, 2020). "This suggests that MED12 mutations are the actual tumor triggering events in uterus." (PMID 30619444, 2018). "Furthermore, we observed that MED12 mutation status was correlated with tumor size and serum Luteinizing hormone levels." (PMID 30619444, 2018). "One likely contributing factor explaining the different results is size bias: in some sample sets large lesions may have been preferred; this selects against MED12-mutation-positive tumours, ones usually smaller in size." (PMID 28432313, 2017). "This reduction in the DNA repair capacity may eventually cause the emergence of mutations such as Med12 in myometrial stem cells converting them into fibroid tumor-forming stem cells; and thereby, leading to the development of UFs." (PMID 26973527, 2016). "In addition to cytogenetic examination, the tumor was also analyzed for MED12 mutations by DNA-sequencing." (PMID 24593849, 2014). "In this work, we examined the role of MED12 exon 2 mutations in other tumour types." (PMID 23132392, 2012). "To analyse whether similar mutations can be found in other tumour types, we collected a broad spectrum of samples for the MED12 exon 2 mutation analyses." (PMID 23132392, 2012). "Furthermore, because race/ethnicity and MED12 mutation of the tumor influence the expression of ncRNAs, individualized therapies could be developed based on these variables." (PMID 40862769, 2025). "Studies to further clarify whether MED12 interacts with CDX4 or HOX genes at chromatin levels and whether the interaction is altered by mut-MED12 will be important in increasing our understanding of mut-MED12–linked tumor growth, which is beyond the scope of the current study." (PMID 37607000, 2023). "Interestingly, distribution of MED12 mutation sites differs in different types of tumor." (PMID 31072327, 2019). "In addition we showed that loss of MED12 in human T-cells leads to decreased apoptosis levels provoked by chemotherapy drugs, further corroborating its role as tumor suppressor in childhood T-ALL and highlighting its putative relapse driving potential in leukemogenesis." (PMID 27602765, 2016).
tumor (continued). "However, the tumors in the South African series tended to be larger, and because the results in the Finnish series had indicated an inverse correlation between MED12 mutations and tumor size, we analyzed the results after correction of this tumor characteristic." (PMID 22182697, 2011). "Parental (H3122) and MED12 KO NSCLC cells (H3122/MED12 KO) were implanted into BALB/c nude (immunodeficient) mice to allow tumor growth." (PMID 40833497, 2025). "To gain a better understanding of the regulatory effects on several tumor-related signaling pathways, we studied the protein expression of MED12, AR, AR-V7 and c-Myc via Western hybridization." (PMID 40133664, 2025). "To gain more insight into the tumor-relevant pathways affected by MED12 knockdown or miRNA modulation, we determined the protein expression of MED12, the androgen receptor (AR), the androgen receptor splice variant V7 (AR-V7) and c-Myc." (PMID 40133664, 2025). "Instead, WNT inhibitory molecules were upregulated in these tumor samples and negative regulation WNT/ β-catenin pathway was observed in MED12 mutant UL associated fibroblast and smooth muscle cells." (PMID 39314474, 2024). "Whole-genome sequencing has demonstrated that a mutation in mediator complex subunit 12 (MED12) is present in up to 70% of uterine fibroids and that there is an association between the rate of MED12 mutations and the tumor number." (PMID 37107181, 2023). "The 1° tumor had eight variants in MKI67, PRKN, PCLO, POLE, CDKN1C, IGSF3, and MED12 genes, which were also present in the brain and spine metastatic cell lines but not present in the parental cell line." (PMID 36900209, 2023). "Further tumor-infiltrating lymphocytes and DDR-related gene analysis revealed anti-tumor immunity in MED12-Mut patients." (PMID 36309740, 2022). "The results are presented by parity (nulliparous and parous) as well as by tumor subtype (MED12 mutant and WT)." (PMID 34521855, 2021). "The findings that MED12 depletion causes resistance of BRCA-deficient cells to chemotherapeutic agents, prompted us to explore if MED12 levels have any impact on the tumor response to genotoxic chemotherapy, in clinical samples." (PMID 34871431, 2021). "Very recently, MED12-mutant mice have been generated, which will offer an opportunity to dissect downstream signaling of Med12 and investigate effects on tumor growth but also on AUB from adjacent endometrial tissue." (PMID 27138351, 2016). "The tumor was also investigated for expression of HMGA2, HMGA1, and MED12 as well as for possible mutations in exon 2 of MED12." (PMID 25621995, 2015). "To extend the analyses we also assessed MED12 expression at mRNA and protein levels and studied tumor genomic profiles and β-catenin localization according to MED12 alterations." (PMID 22768200, 2012). "Herein, we hypothesized that CDK8 activity contributes to the tumor growth of MED12 WT leiomyomas and is influenced by sex steroid hormone kinetics." (PMID 41493967, 2026).
tumor (continued). "Furthermore, genetically engineered CAR-T cells with MED12 KO exhibit increased anti-tumor activity." (PMID 40833497, 2025). "Moreover, DNA methylation changes interact with MED12 mutations to form a regulatory network that modulates progesterone receptor (PR) mediated RANKL expression, promoting stem cell proliferation and tumor growth." (PMID 41463261, 2025). "The results of this study provide a comprehensive profile of protein-coding genes whose expression is altered by the presence or absence of MED12 mutations in the tumor." (PMID 36835153, 2023). "The majority of the tumours (more than 70%) are identified by specific mutations in MED12 exon 2 irrespective of ethnicity." (PMID 37113812, 2023). "The MED12m-positive UFs form the tumor with a rich extracellular matrix and poor blood vessels and smooth muscle cells compared to the MED12m-negative UFs, suggesting MED12 mutations affect the tissue composition of UFs." (PMID 35618793, 2022). "In 5 out of 12 karyotypically abnormal ULs, we detected heterozygous missense mutations in exon 2, while the remaining 7 tumours showed no MED12 mutations." (PMID 34944592, 2021). "In the hormonal study, we have only one tumour without MED12 mutation, which is in agreement with the high frequency of alterations observed for this gene in UL (50–80%)." (PMID 32251338, 2020). "F-box/WD repeat-containing protein 7, FBXW7, mediator complex subunit 12 (MED12), and spen family transcriptional repressor (SPEN), three tumor suppressors associated with the regulation of the NOTCH1 pathway, were also identified as being mutated with low frequency in CLL." (PMID 32182763, 2020). "We demonstrated that RANKL expression is regulated by converging signals from steroid hormone (P4/PR), genetic factors (MED12 mutation), and epigenetic modifications (DNA methylation and histone modification) and contributes to LSC proliferation and tumor formation." (PMID 30538295, 2019). "We found that MED12 was heterogeneously expressed in tumor cells." (PMID 31072327, 2019). "Interestingly, MED12 knockdown led to a strongly increased migratory potential in both cell lines suggesting a tumor suppressive role of MED12 in lung AC." (PMID 27050271, 2016). "By the two latter methods the tumor did neither display clonal karyotypic deviations nor a MED12 mutation akin to those found in a large percentage of UL." (PMID 24593849, 2014). "The most plausible explanation for the apparently normal karyotype in that case is that the tumor cells did not proliferate in vitro as recently also documented for UL carrying MED12 mutations." (PMID 25506394, 2014). "According to the transcriptional repressive and chromatin modifying known functions of MED12, they hypothesize that MED12 could be a tumor suppressor gene, leading to abnormal leiomyomatous growth when mutated." (PMID 22768200, 2012). "The frequency of MED12 mutation was higher when multiple tumors were detected in a single uterus (72.5%; 87/120) as opposed to a single tumor (41%; 9/22) (p<0.01)." (PMID 22428002, 2012). "The only tumor without a somatic second hit was MED12 mutation positive." (PMID 36773604, 2023). "Notably, the tumor-like lesions from MED12 mutant cells contained significantly higher levels of staining (p < 0.001, t test) compared to regenerated tissue from WT cells, indicating substantially more ECM and collagen production in the lesions from MED12 mutant cells." (PMID 37429859, 2023).
tumor (continued). "In LM, MED12 mutant CD49b+ stem cells may symmetrically divide, which induces expansion of the stem cell pool resulting in the abundant CD49b+ cell clusters observed in tumor slices." (PMID 35884847, 2022). "Whether this finding will translate to tumour cells is yet to be investigated; however, it suggests that using ATRi to target ALT in uLMS, as proposed earlier, may not be effective in tumours that also harbour MED12 mutations." (PMID 35326717, 2022). "Regardless of its MED12 mutation status, a single tumour may combine clones with different chromosomal abnormalities and without such abnormalities." (PMID 34944592, 2021). "Moreover, MED12 expression was positively correlated with tumor size (p = 0.036)." (PMID 31072327, 2019). "In summary, our findings suggest that DNA methylation and MED12 mutation together constitute a complex regulatory network that affects progesterone/PR-mediated RANKL gene expression, with an important role in activating stem cell proliferation and fibroid tumor development." (PMID 30538295, 2019). "However, luteinizing hormone showed significant inverse correlation with tumor size (p = 0.008) only in the MED12+ve group compared to the MED12 −ve group This finding indicates that luteinizing hormone may have protective effect against tumor growth." (PMID 30619444, 2018). "Firstly, the location of MED12 expression in tumor cells might depend on the tumor origin." (PMID 28055980, 2017). "MED12 mutation is the leading recurrent oncogenic mechanism demonstrated in both benign and malignant breast PTs, but is less frequent in malignant PTs, suggesting that genetic or epigenetic alterations other than MED12 may play a role in tumor aggressiveness and progression." (PMID 27806318, 2016). "The tumor also expressed MED12 in the absence of exon 2 mutations." (PMID 25621995, 2015). "As a result, the tumor did not display a MED12 mutation as commonly found in UL (data not shown)." (PMID 24593849, 2014). "Through these two genome-wide screens and integration with CRISPR knockout datasets from T cells, MED12, CCNC, and ARIH2 were identified as candidate genes whose knockout enhances the anti-tumor response of NK cells." (PMID 41139700, 2026). "Overexpression of MED12 is highly prevalent in castration-resistant prostate cancer (CRPC) and promotes tumor progression by enhancing AR activity." (PMID 40940746, 2025). "After 9 days of ALK-TKI therapy, sequencing analysis was performed, which identified several tumor suppressor genes, such as NF2 or MED12, and multiple candidate genes." (PMID 37917191, 2023). "Moreover, MED12 mutations found in our cohort do not correlate with cancer progression in most of cases, suggesting that MED12 dysfunction could not be associated with tumor metastasis." (PMID 35347810, 2022). "Moreover, progenitor cells from uLM, but not from the myometrium, carry MED12 mutations, indicating that at least one genetic hit may transform a myometrial stem cell into a tumor-initiating cell and give rise to these benign tumors." (PMID 34445194, 2021). "Effects of MED12 deletion on the proliferation of NSCLC cells were determined by MTT assay and Colony-formation assay in vitro and xenograft tumor model in nude mouse." (PMID 31072327, 2019). "Our data demonstrated that higher MED12 expression correlated with larger tumor volume in NSCLC patients and aborted cytokinesis in MED12 KO cells induced cells senescence and suppressed cell proliferation both in cell culture and mouse xenografts." (PMID 31072327, 2019).
tumor (continued). "In conclusion, this study demonstrates that patients with mCRC with PM have distinct clinical and molecular characteristics compared with those without PM, including differences in histologic grade, tumor location, and presence of MED12 and APC alterations." (PMID 38329392, 2024). "MED12-ULs are presumed to be non-monoclonal and capable of recruiting surrounding wild-type cells to support tumour growth." (PMID 36982825, 2023). "To further determine the role of MED12 in cancer development, we performed xenograft tumor growth assay using three stable PC9 clones with or without MED12 expression." (PMID 31072327, 2019). "Among the few putative driver mutations observed in UL those affecting MED12 and these leading to rearrangements of HMGA2 are particularly frequent and so far never have been reported to coincide within one individual tumor." (PMID 26468330, 2015). "When we looked at the tumor genomic profiles according to MED12 expression data, we observed that all tumors with no MED12 protein expression exhibit very rearranged genomic profiles." (PMID 22768200, 2012). "However, in an orthotopic mouse model implanted with PATC148 tumors, only CCNC and ARIH2 double knockout CAR-NK cells—not MED12-knockout CAR-NK cells—were able to significantly reduce tumor burden." (PMID 41139700, 2026). "Regardless of its MED12 status, a tumor may be comprised of clones with and without chromosomal abnormalities." (PMID 34944592, 2021). "In our study, no MED12 exon mutation was detected in NSCLC samples, whereas we found that MED12 was overexpressed in human NSCLC tissues, which positively correlated with the tumor volume and adversely affected patient survival." (PMID 31072327, 2019). "However, as we observed no insertions in either MED12 mutant or wildtype tumors, other factors such as tumor malignancy and tissue of origin may contribute." (PMID 40264183, 2025). "Lack of MED12 decreased the proliferative potential of NSCLC cells and limited the tumor growth in vivo." (PMID 31072327, 2019).